ITGA2 (integrin subunit alpha 2)
Diseases named in the same sentence as ITGA2 in open-access papers (continued):
Sharing a sentence is not in itself a finding about the gene and the disease.
tumor (continued). "Seven ECMGs (i.e. LAMB3, LAMA3, ITGB6, ITGB4, ITGA2, LAMC2, and COL11A1) were identified to be hub genes of PAAD, which were obviously up-regulated in PAAD and considerably linked to tumor stage as well as prognosis." (PMID 36311789, 2022). "To better demonstrate the role of COL1A1-ITGA2 interaction on the transcriptomic diversity of tumor cells, we now performed co-culture experiments of ITGA2 knockdown tumor cells and COL1A1 silenced TAFs." (PMID 35322024, 2022). "Among the interactions involved in tumor invasion and growth, extracellular matrix interaction scores were higher between tumor stroma and post-treatment tumor (tumor stroma ligand: COL1A1, COL1A2, and COL3A1; post-treatment tumor receptor: ITGA2)." (PMID 36505794, 2022). "These cells highly expressed the integrin family genes associated with the cell adhesion molecule pathway in contrast to epithelial tumor cells, such as ITGA2, ITGA3, ITGA5, ITGA6, and ITGAV, which were among the top-ranking DEGs." (PMID 36553542, 2022). "Given the vast number of cell types within iCCA tumors, our gene expression analyses of iCCA cell lines strongly suggests that iCCA cells are responsible for increased ITGA2 expression within the tumor mass." (PMID 36575207, 2022). "Here, we clearly show that ITGA2 is basically expressed in tumor cells, which was demonstrated by both single-cell transcriptome data and immunohistochemistry detection." (PMID 35719923, 2022). "The high expression in tumor tissue identified ITGA2 as a potential therapeutic target to treatment of cancer." (PMID 35936750, 2022). "In immune therapy, the inhibition of ITGA2 increased the ratio of tumor-killing lymphocytes and decreased the proportion of immunosuppression-related cells in tumors." (PMID 35936750, 2022). "Overexpression of ITGA2 promotes the proliferation and invasion of tumor cells, while its knockdown decreases the degree of these processes." (PMID 34567847, 2021). "Taken together, overexpression of UBE2CP3 promotes tumor progression via cascade amplification of ITGA2 upregulation in GC." (PMID 34274947, 2021). "Disease-free survival analysis showed that tumors with higher expression of ITGA2 or ITGA3 had a shorter time between tumor recurrences." (PMID 34208249, 2021). "Integrin alpha-2 (ITGA2), as an important influencing factor on the tumor immune microenvironment, has the potential to become a molecular marker for targeted therapy and the diagnosis of LGG." (PMID 34778054, 2021). "In contrast to normal glial cells, we also discovered that ITGA2 was notably upregulated in human LGG tumor cell lines." (PMID 34778054, 2021). "ITGA2 has been reported by previous studies to promote tumor progression, both in vivo and in vitro, in many tumors, therefore, playing an essential role in cell migration, invasion, survival, and angiogenesis." (PMID 32202508, 2020). "In the present study, we provided several lines of evidence that support miR-135b-5p function as a tumor suppressor of chemoresistance by targeting ITGA2 in GC." (PMID 32232000, 2020). "In line with a previous finding showing that ITGA2 positively regulates the transcription of fibrillary collagens, the ITGA2-collagen axis would likely constitute a positive feed-back loop between tumor cells and stromal cells in the metastatic niche." (PMID 33026975, 2020). "Taken together, tumor-suppressive miRNAs controls the expression of ITGA2/ITGB1 and ITGA3/ITGB1 in PDAC cells, and the aberrant expressions of these integrins can play pivotal roles in the malignant features of PDAC." (PMID 32899691, 2020). "Overall, the tumor ITGA2 and stromal Tnc is a potential molecular interaction, possibly part of the dual cellular communication among a tumor and its microenvironment cellular types and ECM." (PMID 33334054, 2020). "ITGA2 was mostly expressed in the cytoplasm and the expression was increased in primary tumor compared to normal tissues (p < 0.0045)." (PMID 32824235, 2020).
tumor (continued). "Using multiple cell lines and patient-derived samples, we provide functional evidence that ITGA2 promotes cancer cell adhesion, anoikis resistance, and tumor spheroid-mediated mesothelial clearance in vitro as well as peritoneal metastasis in vivo." (PMID 33026975, 2020). "Our study showed that ITGA2 was markedly overexpressed in several malignant tumor cells and clinical tissues." (PMID 31818309, 2019). "In contrast to previous potential GBM markers, ITGA2 differs by its notable tumor-specific expression and its high expression across multiple cell lines and samples." (PMID 30996239, 2019). "Meanwhile, the combined therapy of anti-PD-1 antibody and Itga2-knockdown increased the populations of tumor-infiltrated CD45+CD8+ T-cells and CD45+CD4+ T-cells further but reduced that of myeloid-infiltrated CD11b+Gr1+ cells in tumors." (PMID 31818309, 2019). "Due to the reduction of Pd-l1 expression after Itga2 suppression, anti-PD-1 antibody treatment manifested a stronger anti-tumor effect in the Itga2 knockdown group by slowing down tumor growth and improving the survival rate of tumor-bearing mice." (PMID 31818309, 2019). "In our current study, we showed that the expression level of ITGA2 was highly related to the ability of proliferation and invasion of tumor cells." (PMID 31818309, 2019). "We have investigated the effects of ITGA2 blockade on inhibiting tumor cell function and have demonstrated a clinical correlation between ITGA2 expression and patient prognosis." (PMID 30996239, 2019). "Our findings also showed that blocking ITGA2 improved tumor immune responses by decreasing the phosphorylation level of STAT3 and suppressing PD-L1 expression in vivo." (PMID 31818309, 2019). "Recent studies have reported that Integrin alpha 2 (ITGA2) plays an essential role in tumor cell proliferation, invasion, metastasis, and angiogenesis." (PMID 31818309, 2019). "Consistent with IHC, comparative analysis with matched non-tumor pancreatic tissues demonstrated that ITGA2 was overexpressed in twelve primary PDAC samples d,e." (PMID 31818309, 2019). "ITGA2 is significantly upregulated in both human GBM tumor tissues and cell lines and is uniformly minimally expressed in normal tissue and cells." (PMID 30996239, 2019). "The colony formation and MTS assays revealed that the inhibition of ITGA2 significantly slowed down tumor growth, whereas ITGA2 overexpression promoted cancer growth in PANC-1 cells c,d." (PMID 31818309, 2019). "Integrin alpha 2 (ITGA2) subunit and the beta 1 subunit form a heterodimer for a transmembrane receptor for extracellular matrix, is an important molecule involved in tumor cell proliferation, survival and migration." (PMID 29743821, 2018). "Based on the results from the present study, it is postulated that altered expression of ITGA2 arising from the polymorphic difference of C807T resulted in increased tumor cell metastasis and intravasation." (PMID 29912899, 2018). "ECM-receptor interaction and focal adhesion pathways were closely related to tumor invasion and metastasis, in which three proteins of ITGA2, COL1A1 and COL11A1 were also behaved up-regulation trend in cancer, except FLNC." (PMID 27626164, 2016). "ITGA2 is a membrane of the integrin-binding family, which is also a significant adhesion molecule in tumor cell invasion." (PMID 27626164, 2016). "Furthermore, by analyzing the TCGA‐THCA dataset, we found that ITGA2 expression was significantly upregulated in tumor tissues and positively correlated with the malignant biological behavior of PTC." (PMID 40985182, 2025). "This study unveils ITGA2+ tumor cells as key drivers of pediatric thyroid cancer aggressiveness." (PMID 40985182, 2025). "Our proteomic and IF findings demonstrate that TuNEPs have enriched cell adhesion proteins BSG and ITGA2, we next investigated whether these proteins impact tumor growth." (PMID 40751052, 2025).
tumor (continued). "Additionally, ITGA2 has been confirmed to increase the proliferation and metastatic potential of various tumor cells by activating the STAT3 signaling pathway." (PMID 40940943, 2025). "However, interestingly, low signal levels in two lectin assays from serum, namely, ITGA2–UEA and ITGB4–MAA, were significantly associated with both tumor recurrence and poor radiotherapy response in ROC analysis as well." (PMID 40287842, 2025). "Notably, studies have shown that ITGA2 overexpression upregulates PD-L1 expression through activation of the STAT3 signaling pathway in several malignant tumor cells, providing direct evidence for ITGA2-mediated remodeling of the immune microenvironment." (PMID 40940943, 2025). "Although we found that decreased expression of ITGA1, ITGA2, or TEAD1 correlated with PCa severity, it remains unclear whether loss of these three genes have synergistic effects on tumor severity compared with loss of either individual gene." (PMID 38169150, 2024). "ITGA2 has been demonstrated to play a significant role in tumor cell proliferation and metastasis." (PMID 39199378, 2024). "Additionally, we analyzed PCa expression data with clinical features, and found that ITGA1/ITGA2 mRNA levels were significantly lower in tumors with high tumor stage, Gleason score, lymph node and elevated PSA levels in multiple distinct patient cohorts." (PMID 38169150, 2024). "ITGA2 functions in the regulation of DDR in PDAC, as well as in the modulation of DNA methylation, a prominent epigenetic modification that influences the expression of tumor-associated markers." (PMID 39568561, 2024). "Taken together, these studies reaffirm our bioinformatics-based analysis and suggest that these extracellular matrix genes (CDH3, COL11A1, COL1A1, COL17A1, KRT19, ITGA2, LAMC2, and SULF1) are highly associated with PDAC tumor carcinogenesis and peritoneal metastasis." (PMID 39682235, 2024). "Interestingly, TEAD1 emerged as the top candidate gene that was co‐expressed with ITGA1/ITGA2 in the TCGA cohort consisting of 498 localized PCa tumor samples." (PMID 38169150, 2024). "Thereafter, we inoculated BxPC-3 and MIA-PaCa2 cell lines into immunodeficient mice to construct a mouse tumorigenic model, and detected the transcription levels of SDC1 and ITGA2, by qRT-PCR, in tumor tissues on the fifth and tenth days after tumorigenesis by qRT-PCR." (PMID 37907515, 2023). "However, we report that significant tumor growth inhibition was achieved by combining ITGA2 knockdown with gemcitabine treatment." (PMID 36765586, 2023). "To test this hypothesis, we observed the sphere formation ability of tumor cells in different concentrations of collagen after knocking down ITGA2." (PMID 35322024, 2022). "Based on previous studies, the present study verified that the overexpression of ITGA2 could promote the proliferation and invasion of tumor cells by regulating the PD-L1 expression." (PMID 35193647, 2022). "Targeting the hub gene ITGA2 attenuated tumor development in a PDAC mouse model." (PMID 35719923, 2022). "In co-culture system of ITGA2 knock-down tumor cells and COL1A1 silenced TAFs, the transcription of CTGF and CYR61 was dramatically reduced in ITGA2-depleted cells, whereas, it was elevated in co-cultured with TAFs and markedly decreased after being treated with the COL1A1 inhibitor." (PMID 35322024, 2022). "ITGA2 was shown to be clearly expressed on the membranes of tumor cells." (PMID 35719923, 2022). "Similarly, IHC staining showed the physical juxtaposition of COL1A1 and ITGA2 in tumor tissue from patient b, which exhibited marked atypia." (PMID 35322024, 2022). "This indicated that ITGA2 could promote the proliferation of tumor cells and inhibit their apoptosis in-vivo." (PMID 35193647, 2022). "In addition, the high expression of ITGA2 in tumor tissue indicates ITGA2 as an important clinical biomarker of poor prognosis in patients." (PMID 35936750, 2022).
tumor (continued). "High risk of tumor recurrence, according to the 2015 American Thyroid Association guidelines, was associated with higher ITGA3 expression, whereas higher expression of ITGA2 and ITGAV correlated with intermediate-risk." (PMID 34208249, 2021). "The overexpression of ITGA2 plays an essential role in tumor progression, metastasis, and motility." (PMID 34262595, 2021). "In our research, we found that YY1 could suppress tumour progression by directly targeted HOXD3 via ITGA2‐ERK cell signalling." (PMID 32557953, 2020). "Besides, expression of ITGA2 increased tumour cell aggression by up‐regulating PD‐L1 via STAT3 signalling pathway." (PMID 32557953, 2020). "This variation in the expression pattern of ITGA2 across different studies may originate from using different types of antibodies and scoring system in addition to tumor heterogeneity of tissue specimens." (PMID 32824235, 2020). "Pie chart summarizes percentage of ITGA2+ tumor spheroids from EOC patients (n = 15)." (PMID 33026975, 2020). "ITGA2 might be involved in tumor transformation or development, and it enriches several signaling pathways related to cell adhesion and migration, but its role in the PI3K/AKT signaling pathway has not been established." (PMID 32202508, 2020). "In this study, we found that ITGA2 inhibition increased the ratio of tumor-killing lymphocytes and decreased the proportion of immunosuppression-related cells in tumors, which suggests that ITGA2 might be an ideal candidate for immune therapy." (PMID 31818309, 2019). "Collectively, these data suggest that ITGA2 could be a potential target for improving the anti-tumor efficiency of immune checkpoint-based therapies in cancer." (PMID 31818309, 2019). "Recently, increasing evidence has suggested that ITGA2 might play an essential role in modulating tumor cell migration, invasion, and metastasis." (PMID 31818309, 2019). "Furthermore, our data demonstrated that knocking down ITGA2 inhibited cancer cell proliferation, but the overexpression of ITGA2 promoted tumor cell proliferation." (PMID 31818309, 2019). "During in vivo GBM therapy, ITGA2-Dox-LPs must cross the BBTB before reaching GBM tumor region." (PMID 30996239, 2019). "Second, ITGA2 may crosstalk with other known resistance mechanisms, such as drug efflux pumps, DNA repair activation, or tumor microenvironment adaptation, which warrants systematic exploration of its synergistic resistance network via multi-omics integration or functional screening approaches." (PMID 40940943, 2025). "Therefore, our work has deciphered a novel mechanism by which TEAD1 regulates α1‐ and α2‐integrin expression and thereby exerts tumor suppressive functions while loss of TEAD1 and/or ITGA1/ITGA2 in PCa genomes were found to correlate with disease progression and aggressiveness." (PMID 38169150, 2024). "Taken together, these results demonstrate prognostic values of ITGA1/ITGA2 loss/del and downregulation upon PCa progression to metastatic stage, suggesting that ITGA1/ITGA2 are new biomarkers that could distinguish aggressive disease and might possess tumor suppressive functions in PCa development." (PMID 38169150, 2024). "Additionally, high expression of ITGA2 was correlated with late-stage tumors and high tumor grade." (PMID 37386391, 2023). "In addition, the presence of epithelial ITGA2+ tumor cells in patient-derived ascites supports the hypothesis on its role in promoting peritoneal dissemination to the collagen-rich niche at the omentum." (PMID 34646995, 2021). "In this study, we report a high abundance of ITGA2 in more than 60% of patients investigated present in primary, ATCs, and omental metastases of the investigated cancer samples, suggesting a selective potential of tumor cell adherence to the collagen-rich omentum." (PMID 33026975, 2020). "Moreover, ITGA2 repression enhanced the tumor inhibition effect of the anti-PD-1 antibody in vivo." (PMID 31818309, 2019).
tumor (continued). "Together these data suggest that TuNEPs induce enhanced outgrowth of tumor cells through adhesion proteins BSG and ITGA2." (PMID 40751052, 2025). "The cell adhesion molecule binding cluster in TuNEPs contained tumorigenic proteins such as ITGA2, CD151, CD9, SLC3A2, and BSG, all known to have an impact on the tumor microenvironment." (PMID 40751052, 2025). "The largest mean differences between tumor and normal tissues were observed in UEA assays ITGA2–UEA, ITGA3–UEA, and ITGB1–UEA." (PMID 40287842, 2025). "In our previous study, we demonstrated that HOXD3 was upregulated in HCC and promoted tumour metastasis by inducing the expression of EGFR and ITGA2 in HCC cells and tissues, indicating that HOXD3 is a crucial angiogenic factor in HCC." (PMID 38493218, 2024). "Many signals favoring tumor cells were significantly activated in C2, such as integrin-related signals (COL9A3 − (ITGA2+ITGB1), JAM3 − (ITGAM+ITGB2), COL6A1 − (ITGA1+ITGB1)), immune suppression signals (CD99 − PILRA), etc.." (PMID 39391717, 2024). "In tumour xenografts, the expression of multiple characteristic SASP factors, including GATA4, MMP2/10, ITGA2 and GBP1, significantly increased after PRC2 inhibition, contributing to ECM remodelling and tumour regression." (PMID 39270064, 2024). "The results constantly showed that PCa patients with triple low expression of ITGA1, ITGA2 and TEAD1 demonstrated higher Gleason score, PSA levels, advanced tumor stages and lymph node metastasis." (PMID 38169150, 2024). "Among these genes, six genes are potential regulator of tumor metastasis, including CEMIP, FBN2, TIAM1, ITGA2, ARHGAP42, and GPRIN3." (PMID 38971758, 2024). "The other network included products of genes associated with tumour growth and cell proliferation (FN1, VEGFA), tumour progression and metastasis (CD44, ITGA2) and immune inhibition (NT5E)." (PMID 36649303, 2023). "Regression analysis of tumor tissue volume and expression of SDC1 and ITGA2 showed a positive correlation ed with the expression of SDC1 and ITGA2." (PMID 37907515, 2023). "ITGA2, an ECM receptor, is a transmembrane protein that promotes ECM remodeling and enhances tumor invasive potential." (PMID 38125763, 2023). "Since the increased stiffness of the tumor is mainly mediated by CAFs, further studies with co-cultures of PDAC-resistant cells and CAFs will deepen our understanding of the role of ITGA2-increased expression in the TME." (PMID 36765586, 2023). "In single-cell sequencing analysis, ITGA2, ITGA3, ADAM9, and BHLHE40 were all highly expressed in malignant ductal cells, suggesting important roles in tumor progression." (PMID 37377917, 2023). "We found that the key genes, especially SDC1, SDC4, ITGA2, and ITGA3, in malignant cells that interacted with CAFs and Angiogenic_EC were positively correlated with the pEMT score in tumor cells." (PMID 38002057, 2023). "We also explored the protein expression level of PRKCI and ITGA2 in the Human Protein Atlas (HPA) database, and found that the expression level of both genes were significantly higher in tumor tissue than in normal tissues." (PMID 37386391, 2023). "To investigate whether the pEMT biological process is potentially caused by SDC1, SDC4, ITGA2, and ITGA3 expressed by CAFs, we further focused on the correlation between the ligand genes from CAFs as well as from Angiogenic_EC with the abundance of malignant tumor cells undergoing pEMT." (PMID 38002057, 2023). "We then analyzed the expression profiles of COL1A1, COL4A1, and COL6A2 in TAF and ITGA2, ITGAV, and ITGA1 in tumor cells." (PMID 35322024, 2022). "ITGA2 interacted with COL1A1, COL1A2, COL8A1, FN1, and HSPG2, mediating the tumor cell–fibroblast and tumor cell–endothelial cell connection." (PMID 35719923, 2022). "A particularly interesting potential interaction with high relevance for tumor biology includes JAG2 (cancer) with NOTCH3 (mouse stroma), and interactions of integrins (ITGA2, ITGA2B) with ECM proteins (COL2A1, LAMA1)." (PMID 35053442, 2022).